NLRP2 (NLR family pyrin domain containing 2)
Description:
Suppresses TNF- and CD40-induced NFKB1 activity at the level of the IKK complex, by inhibiting NFKBIA degradation induced by TNF. When associated with PYCARD, activates CASP1, leading to the secretion of mature pro-inflammatory cytokine IL1B. May be a component of the inflammasome, a protein complex which also includes PYCARD, CARD8 and CASP1 and whose function would be the activation of pro-inflammatory caspases.
Synonyms: NALP2; NBS1; PAN1; PYPAF2; FLJ20510; CLR19.9; OZEMA18
Tractability: Small molecule: a structure with a bound ligand is known. PROTAC: ubiquitination databases record sites on it; its protein half-life has been measured.
Gene: Protein-coding gene on chromosome 19 (54,953,130 to 55,001,142, forward strand). Ensembl gene ENSG00000022556.
Subcellular location: Cytoplasm
Subcellular location (Human Protein Atlas): Cytosol; Golgi apparatus; Vesicles
Gene Ontology:
Molecular function: protein binding; Pyrin domain binding
Biological process: negative regulation of non-canonical NF-kappaB signal transduction; positive regulation of interleukin-1 beta production; establishment of spindle localization; positive regulation of embryonic development; regulation of inflammatory response; regulation of interleukin-1 beta production
Cellular component: chromosome, telomeric region; cytoplasm; cytosol; cell cortex; subcortical maternal complex
Genetic constraint (gnomAD): Loss-of-function variants: 100 observed, 95.88 expected, observed/expected ratio (o/e) 1.04, 90% interval 0.89 to 1.23. The upper end of that interval is the gene's LOEUF score, 1.23, which puts it in group 5 of 6, group 1 being the genes least tolerant of losing a copy. Missense variants: 1,459 observed, 1,353.2 expected, observed/expected ratio (o/e) 1.08, 90% interval 1.03 to 1.13. Synonymous variants: 649 observed, 563.07 expected, observed/expected ratio (o/e) 1.15, 90% interval 1.08 to 1.23.
Homologues: Orthologues: chimpanzee NLRP2 (99% identical), macaque NLRP2 (86% identical), rat Nlrp2 (43% identical), mouse Nlrp2 (43% identical). Paralogues in human: NLRP7 (62% identical), NLRP14 (28% identical), NLRP11 (26% identical), NLRP3 (26% identical), NLRP13 (24% identical), NLRP12 (24% identical), NLRP5 (24% identical), NLRP4 (22% identical), NLRP8 (21% identical), NLRP9 (21% identical), NLRP1 (21% identical), NLRC5 (18% identical), and 8 more.
Diseases named in the same sentence as NLRP2 in open-access papers:
NLRP2 is named in the same sentence as 72 diseases in open-access papers, as found by Europe PMC text mining. Sharing a sentence is not in itself a finding about the gene and the disease. The quoted sentences say what the papers report.
hydatidiform mole (8 papers, 2009 to 2022). A gestational trophoblastic disorder characterized by marked enlargement of the chorionic villi, hyperplasia of the villous trophoblastic cells and hydropic changes. "Mutations of other NLRP family genes, such as NLRP7 and NLRP2, in parent’s genome result in familial hydatidiform mole and multisite imprinting disorder, respectively." (PMID 32216802, 2020). "Maternal-effect mutations of other human NLRP genes, NLRP7 and NLRP2, cause familial biparental hydatidiform mole and multilocus imprinting disturbance, respectively." (PMID 26323243, 2015). "In humans, the primary presentation of NLRP2 maternal effect mutations, is a Beckwith-Wiedemann phenotype in offspring, whereas mutations in NLRP7 cause recurrent biparental hydatidiform moles, a placental developmental phenotype." (PMID 28317850, 2017). "In this sense, mutations in some genes lead to multilocus loss of methylation: ZFP57 in TNDM patients, NALP7 and C6orf221 in familial biparental hydatidiform mole, or NLRP2 in a family with BWS." (PMID 26106604, 2015). "Pathological variants of zinc finger protein genes such as ZFP57 and ZNF445 and of genes related to the subcortical maternal complex such as NLRP2, NLRP5, NLRP7, and KHDC3L have been identified in cases of multilocus imprinting disturbances (MLIDs) and recurrent hydatidiform moles (RHMs)." (PMID 35581658, 2022). "Although there is currently no clear evidence implicating NLRP2 in trophoblast development, mutations of NLRP7 have been reported to cause recurrent hydatidiform moles, an abnormality of pregnancy that is characterized by hypertrophic vesicular trophoblasts in human." (PMID 25889179, 2015). "The involvement of NLRP2 and NLRP7 in inflammasome inhibition and a connection between their presence among maternal RNAs in oocytes and the formation of hydatiform moles, a form of reproductive failure, further suggest that some NLRs may have roles in both inflammation and reproductive success." (PMID 21362197, 2011).
depression (6 papers, 2021 to 2025). "Intraperitoneal injection of kynurenine activated astrocytic NLRP2 inflammasome and induced depression-like behaviors in mice." (PMID 40108901, 2025). "Knocking-out kynurenine and/or NLRP2 hampers inflammation and restores homeostasis, which suggests that drugs targeting kynurenine or NLRP2 in depression-like behaviors would relieve from these states." (PMID 38644450, 2024). "Disturbances of kynurenine metabolites are associated with neuroimmune disturbance, as elevated kynurenine induced depression-like behaviors in rodents through monocyte trafficking and regulation of the NLRP2 inflammasome in astrocytes." (PMID 34471249, 2021). "Not unexpectedly, the role of astroglial NLRP2 has also been reported in chronic mild stress induced depression, where they introduced an intraperitoneal injection of tryptophane derived metabolite kynurenine (Kyn), which upregulated NLRP2 in hippocampal primary astrocytes cultures." (PMID 38722788, 2024). "Besides, kynurenine, a tryptophan metabolite produced as a biomarker in the immune dysfunction of depression, was recently shown to activate NLRP2 inflammasome in astrocytes." (PMID 38644450, 2024).
glioma (5 papers, 2022 to 2024). A benign or malignant brain and spinal cord tumor that arises from glial cells (astrocytes, oligodendrocytes, ependymal cells). "Inhibition of P2X7 and pannexin 1 also reduces the inflammatory response of gliomas by inhibiting the expression of the NLRP2 inflammasome." (PMID 37723542, 2023). "These PRGs, which are upregulated in gliomas, include caspase-3 and caspase-9, n-terminally truncated gasdermin D (GSDMD), and the inflammasome proteins NLRP2 (“NLR family pyrin domain containing 2”) and NLRC4 (“NLR family CARD domain containing 4”)." (PMID 39062119, 2024). "Some studies have focused on the presence and function of NLRP2 and NLRP7 in other tumors, but their presence in glioma is rare." (PMID 37723542, 2023). "Three genes (NLRP2, NLRP9, and GSDMB) were downregulated, while the remaining 54 genes were upregulated in the glioma group." (PMID 35547808, 2022).
ischemic stroke (5 papers, 2020 to 2024). A stroke disorder caused by obstruction of blood flow to the brain, due to thrombotic (local blood clot formation) or embolic (due to a blood clot or other material traveling from another site) event. "Some works focus on the role of NLRP2 in the reproductive system, in embryonic development and in ischemic stroke." (PMID 34768839, 2021). "Low constitutive NLRP2 levels were observed in the cortex, hippocampus and striatum, which were significantly elevated following occlusion of middle cerebral artery mimicking ischemic stroke." (PMID 38722788, 2024). "In addition, higher expression levels were discovered both in vitro and in vivo under ischemic stroke conditions, further confirming the contribution of NLRP2 in ischemic stroke." (PMID 36297283, 2022). "In conclusion, further clinical studies should be conducted that deepen the relationship between clinical signs and ischemic stroke symptomatology and the expression levels of NLRP3 inflammasomes, NLRP1, NLRP2, and NLRC4 in damaged brain tissue." (PMID 36297283, 2022). "Finally, we reviewed other inflammasomes such as NLRP1, NLRP2, and NLRC4, the functions of which need to be clarified in the context of pathogenetic mechanisms that aggravate the sequelae of ischemic stroke." (PMID 36297283, 2022). "In addition, we provide some information regarding the contribution of NLRP1, NLRP2, and NLRC4 inflammasomes to ischemic stroke pathogenesis, highlighting potential therapeutic strategies that require further study." (PMID 36297283, 2022). "Recent studies showed that various inflammasomes, containing NLRP1, NLRP2, NLRP3, NLRP10, NLR family card domain containing 4 (NLRC4), and absent in melanoma 2(AIM2) 35-39, are activated in ischemic stroke." (PMID 32788872, 2020).
lung adenocarcinoma (5 papers, 2022). A carcinoma that arises from the lung and is characterized by the presence of malignant glandular epithelial cells. "Similarly, NOD1 and NLRP2 function as risk genes in pyroptosis-related prognostic gene signature related to pyroptosis of lung adenocarcinoma." (PMID 36457716, 2022). "In another study of pyroptosis, NLRP2 was also used to identify the PRG score for predicting the prognosis of lung adenocarcinoma, and Li etal." (PMID 35756629, 2022). "not only constructed a pyroptosis-related prognostic predication model involving 5 PRGs (CASP6, NLRP7, NOD1, NLRP1, and NLRP2) in lung adenocarcinoma, but also established a network of mRNA–miRNA–lncRNA closely relating to PRGs." (PMID 35912258, 2022). "A lung adenocarcinoma study has reported that low expression of NLRP2 is correlated with poor survival rates in lung adenocarcinoma (p = 0.014)." (PMID 35055428, 2022). "Another comprehensive bioinformatics analysis also performed on lung adenocarcinoma identified a prognostic pyroptosis-related gene signature containing five genes (NLRP7, NLRP1, NLRP2, NOD1, and CASP6)." (PMID 36324154, 2022).
periodontitis (5 papers, 2015 to 2025). An acute or chronic inflammatory process that affects the tissues that surround and support the teeth. "Similarly, the study demonstrated a clear and distinct correlation between rs35829419 C>A in NLRP3 and rs17699678 C>T in NLRP2 polymorphism and periodontitis in the form of an increased CAL index." (PMID 26253076, 2015). "The expression of NLRP3, NLRP2, IL-1β, and IL-18 in gingival tissues from patients with gingivitis, chronic periodontitis, and aggressive periodontitis was upregulated, with positive correlations observed between NLRP3 and its downstream products." (PMID 41440367, 2025). "The results obtained showed the distribution of two polymorphisms of NLRP2 (rs17699678 C>T) and NLRP3 (rs35829419 C>A) genes in Polish subjects with pancreatic diseases and periodontitis." (PMID 26253076, 2015). "However, NLRP2 mRNA levels are increased in gingival tissues from patients with chronic periodontitis and generalized aggressive periodontitis but reduced in Mono-Mac-6 cells infected with P. gingivalis." (PMID 34177950, 2021). "Moreover, the current study introduces research on a group of patients with conditions that have never been analyzed before in the context of NLRP2 and 3 polymorphisms: periodontitis, chronic pancreatitis, and pancreatic cancer." (PMID 26253076, 2015). "In order to observe the different distribution of NLRP family intuitively, immunohistochemistry was applied to analyze the expression characteristics of NLRP1, NLRP2, NLRP3, NLRP6, and NLRP12 in full-thickness gingival tissue samples obtained from severe periodontitis patients and healthy people." (PMID 32903638, 2020).
bipolar disorder (3 papers, 2017 to 2025). A disorder of the brain that causes unusual shifts in mood, energy, activity levels and the ability to carry out day-to-day tasks. "NLR family pyrin domain containing 2 (NLRP2) has been reported to be upregulated in iPSCs in bipolar disorder–associated (BD-associated) inflammation." (PMID 40111412, 2025). "NLRP2 gene dysregulation was shown to be involved in human fetal brain development indicating a robust difference between cases of bipolar disorder and healthy individuals." (PMID 38722788, 2024).
bladder cancer (3 papers, 2021 to 2022). "Also, NLRP2 revealed TSG functions in glioblastoma and oncogenic functions in bladder cancer." (PMID 34257569, 2021).
Cerebral ischemia (3 papers, 2018 to 2022). Restriction of arterial blood supply to the brain associated with insufficient oxygenation to support the metabolic requirements of the tissue. "The NLRP2 inflammasome, which was initially described in human astrocytes, also contributes to the inflammatory response after cerebral ischemia in mice." (PMID 30233311, 2018). "However, the cellular distribution of NLRP2 in the CNS and its relation to neurological disorders such as pathological pain and cerebral ischemia still need to be further explored." (PMID 34768839, 2021). "Both NLRP2 and NLRP3 have been shown to participate in the proinflammatory events related to experimentally induced cerebral ischemia after cerebral ischemia-reperfusion injury and acrolein-induced astrocytic inflammation in brain affected by ischemic stroke." (PMID 35783102, 2022).
COVID-19 (3 papers, 2021 to 2023). A disease caused by infection with severe acute respiratory syndrome coronavirus 2. "In addition, we found differential DNA methylation patterns by COVID-19 status for genes, such as NLRP2 and ACE2 in an exploratory analysis of an empirical data set reporting on human COVID-9 infections." (PMID 34895312, 2021). "Furthermore, male–female expression differences in NLRP2 were also validated in blood highlighting that NLRP2 displayed a consistent sex-biased expression pattern across multiple tissues relevant in COVID-19 biology." (PMID 34895312, 2021). "Furthermore, one CpG site in NLRP2 (cg20995778; p value ≤ 0.05 and Δβ > 0.05) was differentially methylated in males when COVID-19 positive cases were compared to COVID-19 negative controls." (PMID 34895312, 2021). "Thus, NLRP2 participates in a negative feedback loop to suppress a hyperactive immune response, which is often observed in COVID-19 patients." (PMID 34895312, 2021). "While the role of NLRP2 is not specifically characterized in SARS-CoV-2 infection, NLRP2 has shown sex-biased expression in influenza infection, and another member of the same NOD-like receptor family, NLRP3, is involved in inducing pulmonary inflammation in COVID-19." (PMID 34895312, 2021).
glioblastoma (3 papers, 2021). The most malignant astrocytic tumor (WHO grade IV). "An interesting feature of the NLRP2 inflammasome is that it has been shown to attenuate NF-κB activity macrophages, trophoblasts and glioblastoma cell lines." (PMID 34768839, 2021). "Also, NLRP2 inhibits cell proliferation and tumor growth of human glioblastoma." (PMID 34257569, 2021).
pancreatic cancer (3 papers, 2015 to 2023). "As a result, five highly expressed PRGs, including apoptotic-related genes (BAK1 and TP63), CHMP4C, IL18, and NLRP2, were categorized as high risk in this prognostic model and provided poor prognoses for pancreatic cancer." (PMID 37893166, 2023). "Our study demonstrated that the prevalence of rs35829419 (Q705K, NLRP3) polymorphism is higher in subjects with pancreatic cancer and that of rs17699678 (F359L, NLRP2) polymorphism is higher in the group of chronic pancreatitis." (PMID 26253076, 2015). "In conclusion, the study revealed that the NLRP2 polymorphism was associated with chronic pancreatitis, whereas the NLRP3 polymorphism was comorbid with pancreatic cancer." (PMID 26253076, 2015). "Finally, to evaluate the risk and prognosis in pancreatic cancer more conveniently using pyroptosis-related genes, we constructed a prognostic model consisting of seven PRGs, including CASP4, GSDMC, NLRP1, PLCG1, IL-18, CASP1 and NLRP2." (PMID 35712482, 2022). "Therefore, the aim of this study was to evaluate periodontal status in reference to a single-nucleotide polymorphism (SNP) of NLRP2: F359L (rs17699678 C>T) and NLRP3: Q705K (rs35829419 C>A) in patients with pancreatic cancer and chronic pancreatitis as well as in the control group." (PMID 26253076, 2015). "According to this study, PRGs risk models were defined with the combination of immune and signaling pathways genes (CASP4, GSDMC, NLRP1, PLCG1, IL-18, CASP1, and NLRP2), among which CASP4, NLRP1, PLCG1, IL-18, and CASP1 are overexpressed in pancreatic cancers." (PMID 37893166, 2023). "An additional risk model PRG based on more immune-related genes (CASP4, GSDMC, IL-18, NLRP1, NLRP2, PLCG1, TIRAP, and TNF) was developed, which can be used to predict pancreatic cancer prognosis with an accuracy of medium to high." (PMID 37893166, 2023).
Alzheimer disease (2 papers, 2014 to 2017). A progressive, neurodegenerative disease characterized by loss of function and death of nerve cells in several areas of the brain leading to loss of cognitive function such as memory and language. "NLRP2 appears dysregulated in astrocytes, and NLRP3 in microglia in the context of Alzheimer’s disease as well as in other neurological diseases like Parkinson’s disease; additionally, NLRP2/3 are altered in pathologies that show comorbidity with AD: obesity, type-2 diabetes." (PMID 29078805, 2017).
atopic dermatitis (2 papers, 2013 to 2021). "Although, NLRP2 is not highly expressed in human or mouse skin, association of decreased NLRP2 expression with early onset atopic dermatitis was described due to promoter hypermethylation in immune cells of the patients." (PMID 33925158, 2021). "Additionally, NLRP2 and IL-1β expression was more upregulated in human hair follicle-derived keratinocytes from atopic dermatitis patients than controls and it would be of interest to further explore whether the NLRP2 inflammasome plays a role in atopic dermatitis-associated inflammation." (PMID 33925158, 2021). "We hypothesized that overexpression of IL32 in hair follicle keratinocytes of patients with atopic dermatitis would lead to the excessive production of pro-IL1β and that the activation of IL1β from pro-IL1β by inflammasome complex, in which NLRP2 protein might be involved, would be augmented." (PMID 23385231, 2013).
Beckwith-Wiedemann syndrome (2 papers, 2009 to 2015). Beckwith-Wiedemann syndrome (BWS) is a genetic disorder characterized by overgrowth, tumor predisposition and congenital malformations. "A homozygous mutation in NLRP2 was found to be responsible for the imprinting disorder Beckwith-Wiedemann syndrome (BWS) in two offspring of the affected mother." (PMID 26121690, 2015).
breast carcinoma (2 papers, 2020 to 2021). "On the other hand, low expression of TTF2, ABCC2, FLOT2, and NLRP2 was correlated with poor prognosis in HER2-positive breast cancer patients, whereas their low expression was correlated with better prognosis in the overall METABRIC cohort." (PMID 32640677, 2020). "Furthermore, CASP8 (2%), NLRC4 (1%), NLRP3 (1%), NLRP2 (1%), PLCG1 (1%), NLRP1 (1%), NLRP7 (1%), SCAF11 (1%), GSDMC (1%), and NOD1 (1%) occurred somatic mutations as well as most of them had high frequencies of CNV in breast cancer." (PMID 34589498, 2021).
Crohn disease (2 papers, 2014 to 2021). A gastrointestinal disorder characterized by chronic inflammation involving all layers of the intestinal wall, noncaseating granulomas affecting the intestinal wall and regional lymph nodes, and transmural fibrosis. "Polymorphisms in other NLR and related genes have been implicated in diseases that share clinical features with SpA, including Behçet's disease, Crohn's disease and psoriatic arthritis, while reduced NLRP2 expression was found in adults with axial spondyloarthritis." (PMID 25506924, 2014).